LMNB2 (lamin B2)
Diseases named in the same sentence as LMNB2 in open-access papers (continued):
Sharing a sentence is not in itself a finding about the gene and the disease.
lipoma (2 papers, 2021 to 2024). A benign, usually painless, well-circumscribed lipomatous tumor composed of adipose tissue. "Among the candidate selection signal genes, the LIM domain containing the preferred translocation partner in lipoma (LPP), immunoglobulin superfamily member 11 (IGSF11), and lamin B2 (LMNB2) genes has been associated with immune responses and disease sensitivity." (PMID 34072132, 2021).
liver cancer (2 papers, 2021 to 2025). An epithelial or non-epithelial malignant neoplasm that arises from the liver. "This suggested that LMNB2-mediated immune evasion in liver cancer might be linked to PD-L1 expression." (PMID 40483310, 2025). "Moreover, TIMER database analysis of immune infiltration in liver cancer revealed that high LMNB2 expression was frequently associated with reduced immune cell infiltration in the tumor microenvironment." (PMID 40483310, 2025). "The underlying mechanism of LMNB2 overexpression in liver cancer remains unclear." (PMID 40483310, 2025). "In co-culture experiments with Jurkat cells and liver cancer cell lines (Huh7 and HepG2) with varying LMNB2 expression levels, elevated LMNB2 was found to substantially induce T cell apoptosis and cell cycle arrest." (PMID 40483310, 2025). "To delineate the pathways through which LMNB2 impacts liver cancer, we performed RNA-seq on Huh7 cells with LMNB2 knockdown and corresponding control cells." (PMID 40483310, 2025). "Data retrieved from the TCGA and GEO databases (GSE76427 and GSE45627) revealed markedly higher LMNB2 levels in liver cancer tissues than in normal liver tissues." (PMID 40483310, 2025). "Analysis of tumor weight and volume indicated that LMNB2 significantly drove liver cancer tumor progression." (PMID 40483310, 2025). "LMNB2 belongs to the lamin family and is closely related to occurrence, development, and prognosis of liver cancer." (PMID 34386038, 2021). "Moreover, ST profiling and IHC analysis validated the positive correlation between LMNB2 and PD-L1 in liver cancer." (PMID 40483310, 2025). "Notably, the PD-L1 signaling pathway was markedly downregulated in liver cancer cells following LMNB2 knockdown." (PMID 40483310, 2025). "Moreover, our analysis uncovered that LMNB2 is significantly upregulated in liver cancer and exhibits a strong correlation with unfavorable prognosis." (PMID 40483310, 2025). "Importantly, IHC staining analysis revealed a negative correlation between SPOP and LMNB2 expression in liver cancer tissues." (PMID 40483310, 2025).
microcephaly (2 papers, 2021). A congenital or acquired developmental disorder in which the circumference of the head is smaller than normal for the person's age and sex. "Here we report the identification of recurrent heterozygous variants in LMNB1 and LMNB2, implicating the nuclear lamina in the etiology of microcephaly." (PMID 33033404, 2021). "Here we identify recurrent and de novo heterozygous variants in LMNB1 and LMNB2 in eight microcephaly patients from the DDD cohort." (PMID 33033404, 2021). "Following identification of variants in LMNB1, we assessed whether variants in its close homolog LMNB2 were also associated with microcephaly." (PMID 33033404, 2021).
prostate carcinoma (2 papers, 2017 to 2025). A carcinoma that arises from epithelial cells of the prostate gland. "We further generated 5 prostate cancer–associated SPOP mutants, and co-IP assays revealed that all 5 mutants showed impaired binding to LMNB2 compared with WT SPOP." (PMID 40662365, 2025).
thyroid carcinoma (2 papers, 2024 to 2025). "When para-cancerous tissue was compared with non-cancer tissue, LMNB2 mRNA showed high expression levels in all types of cancers, expect in adenoid cystic carcinoma (ACC), pheochromocytoma and paraganglioma (PCPG) and thyroid carcinoma (THCA)." (PMID 39774004, 2024).
type II diabetes (2 papers, 2015 to 2021). "We describe here a rare mutation (c.700C > T; p.(Arg234Trp)) in LMNB2 in a patient suffering from a central obesity associated with hypertriglyceridemia and type 2 diabetes, acanthosis nigricans, and liver steatosis—all signs overlapping with genetic partial lipodystrophy syndrome." (PMID 35011612, 2021).
uterine carcinosarcoma (2 papers, 2022 to 2024). A usually aggressive malignant neoplasm arising from the uterine corpus and less often the cervix. "Interrogating Uterine Corpus Endometrial Carcinoma (TCGA-UCEC) and Uterine Carcinosarcoma (TCGA-UCS) cohorts revealed NCL to be the most highly upregulated gene in carcinosarcoma, with S100A11, LMNB2, RERG, E2F1 and CCNA2 representing key dysregulated NAGs in EC." (PMID 35682908, 2022).
acute myeloid leukemia (1 paper, 2024). Acute myeloid leukemia (AML) is a group of neoplasms arising from precursor cells committed to the myeloid cell-line differentiation. "In acute myeloid leukemia (LAML), LMNB2 mRNA was down-regulated in cancer tissues when compared with normal tissues." (PMID 39774004, 2024).
breast tumor (1 paper, 2023). "There was a slight downregulation of LMNA in breast tumor tissues while LMNB1 and LMNB2 were significantly upregulated." (PMID 37218524, 2023).
colon cancer (1 paper, 2021). "Study of other genes revealed that LMNB2 showed an interaction with the MYC gene, and the overexpression of this nuclear protein was reported to inhibit colon cancer cell migration and interaction with chromatin." (PMID 34830168, 2021).
diabetes (1 paper, 2021). "Four genes including GAB2, LMNB2, XAB2 and RBM39 are involved in the regulation of diabetes, fat and insulin signaling, according to text mining." (PMID 34084770, 2021).
diffuse large B-cell lymphoma (1 paper, 2024). "LMNB2 expression was positive associated with MSI in LUSC, UCEC, STAD, UCS, LUAD, PRAD, kidney renal clear cell carcinoma (KIRC), KICH, testicular germ cell tumors (TGCT) and SARC, but negatively associated with MSI in READ and lymphoid neoplasm diffuse large B-cell lymphoma (DLBC)." (PMID 39774004, 2024).
epilepsy (1 paper, 2023). A brain disorder characterized by episodes of abnormally increased neuronal discharge resulting in transient episodes of sensory or motor neurological dysfunction, or psychic dysfunction. "Separately from this complex, the LMNB2 gene mutations are often accompanied by epilepsy, and this gene is also involved in epigenetic regulation, directly affecting chromatin and the structure of the nucleus." (PMID 36982355, 2023).
frontotemporal dementia (1 paper, 2025). Frontotemporal dementia (FTD) comprises a group of neurodegenerative disorders, characterized by progressive changes in behavior, executive dysfunction and language impairment, as a result of degeneration of the medial prefrontal and frontoinsular cortices. "The Lamin B2 signature also presented in anterior horn, spinal cord neurons from post-mortem ALS ± frontotemporal dementia patient tissue possessing G38R and D40G protein variants." (PMID 38989900, 2025).
hearing loss (1 paper, 2025). "Therefore, research on LMNB2 not only provides new insights into the mechanisms of sensorineural hearing loss but also offers potential targets for future therapeutic strategies." (PMID 40001646, 2025).
infertile (1 paper, 2017). "DMRTB1 was a down-regulated common gene among MArrest, oligospermia and Ikbkap KO, GPR137B was common among teratospermia, Bcl6b and Pou3f1 KD, and LMNB2 was common among Bcl6b, Etv5 and Pou3f1 KD infertile mice." (PMID 29150651, 2017).
lymph node metastasis (1 paper, 2021). "The high expression of LMNB2 protein was positively correlated with tumor diameter (P < 0.001), TNM stage (P < 0.001), lymph node metastasis (P = 0.003), distant metastasis (P = 0.039), and depth of invasion (P = 0.015)." (PMID 33782407, 2021).
muscular dystrophies (1 paper, 2018). "Mutations in human Lamin genes (LMNA, LMNB1, LMNB2) lead to a wide-range of diseases including muscular dystrophy, peripheral neuropathy and progeria." (PMID 31225490, 2018).
prostate tumors (1 paper, 2025). "To further assess the impact of SPOP mutations on LMNB2 protein levels in patient specimens, we analyzed 100 primary prostate tumors from our cohort." (PMID 40662365, 2025).
sarcoma (1 paper, 2024). A usually aggressive malignant neoplasm of the soft tissue or bone. "Better understanding is gained on SARC pathogenesis and the possible significance of LMNB2 as a therapeutic target for sarcoma." (PMID 39774004, 2024).
stomach adenocarcinoma (1 paper, 2024). "However, in thymoma (THYM) and stomach adenocarcinoma (STAD), the up-regulation of LMNB2 was related to a better OS, which meant LMNB2 seemed to have a more protective role in these two cancers." (PMID 39774004, 2024).
virus infection (1 paper, 2017). "Meanwhile, only three proteins that displayed regulated expression in both H5N1-infected CEF cells at all the time points were ACTG1, LMNB2 and vimentin, which are cytoskeleton protein that is generally expressed in normal cells and reorganized after virus infection." (PMID 28079188, 2017).
cancer (18 papers, 2015 to 2025). A tumor composed of atypical neoplastic, often pleomorphic cells that invade other tissues. "In the present study, we showed that cancer-associated SPOP mutations increased nuclear size by decreasing LMNB2 protein levels." (PMID 40662365, 2025). "We also showed that cancer-associated mutations in SPOP led to decreased levels of LMNB2 and compromised NE integrity, making SPOP-mutant cells more susceptible to NE rupture and vulnerable to farnesyltransferase inhibition." (PMID 40662365, 2025). "In this study, we demonstrated that cancer-associated speckle-type POZ protein (SPOP) mutations enlarged nuclear size by reducing the protein level of lamin B2 (LMNB2), a key nuclear integrity protein." (PMID 40662365, 2025). "Cancer-associated SPOP mutations increase nuclear size by reducing LMNB2, compromising nuclear envelope integrity and potentially sensitizing tumors to farnesyltransferase inhibitor therapies." (PMID 40662365, 2025). "We found that LMNB2 expression showed a significant positive association with the cell cycle, differentiation, invasion, metastasis and proliferation in most types of cancers." (PMID 39774004, 2024). "LMNB2 showed varying degrees of association with RNAs and DNAs in different cancer types and the expression level of LMNB2 showed positive correlation with RNAss and DNAss in SARC." (PMID 39774004, 2024). "LMNB1 and LMNB2 are coding genes for lamin B1 and lamin B2, respectively, which are nucleoskeleton components associated with cancer and aging." (PMID 32948197, 2020). "However, SPOP mutations led to enhanced LMNB2 degradation and disrupted NE integrity, causing nuclear rupture and making cancer cells more sensitive to farnesyltransferase inhibitor–based (FTI-based) therapies." (PMID 40662365, 2025). "Finally, the association among LMNB2 expression levels and different immune markers across cancers was analyzed." (PMID 39774004, 2024). "However, in STAD and THYM, high expression of LMNB2 was associated with better OS, suggesting that LMNB2 has a more protective role in both cancers." (PMID 39774004, 2024). "Little is known about role of lamin B2 and its association with cancer." (PMID 26469707, 2015). "LMNB1 is degraded through the lysosome, but the regulation of LMNB2 in cancer is less well understood." (PMID 40662365, 2025). "Collectively, our data showed that cancer-associated SPOP mutation increased nuclear volume, likely through direct binding with LMNB2." (PMID 40662365, 2025). "Abnormal expression of LMNB2 has been identified in multiple types of cancers, likely due to the impact on cellular proliferation and DNA damage repair." (PMID 39152463, 2024). "Next, we studied the expression of the LMNB2 gene in the NCI-60 cancer cell line panel and systematically tested the correlation between its expression level and the sensitivity of more than 200 chemotherapeutic drugs." (PMID 39774004, 2024). "Our data showed that LMNB2 mRNA has a high expression in almost all types of cancer, with the exception of PAAD and PCPG, when compared with both adjacent and normal tissues." (PMID 39774004, 2024). "Epigenetic modification plays an important role in mRNA expression level, we thus examined the methylation status of LMNB2 in pan-cancer." (PMID 39774004, 2024). "Overexpression of LMNB2 has been found in a range of cancers and abnormal expression of LMNB2 often contributes to cancer progression." (PMID 39774004, 2024). "In this study, we demonstrated that LMNB2 expression is associated with TMB and MSI in several cancer types." (PMID 39774004, 2024). "The TISIDB database was also used to check the correlation of LMNB2 expression with lymphocytes, immunomodulators and chemokines in pan-cancer." (PMID 39774004, 2024). "In conclusion, our study shows that the expression profile of LMNB2 has significant prognostic value in pan-cancer, especially SARC." (PMID 39774004, 2024).
cancer (continued). "This study reports on LMNB2 expression in pan-cancer and particularly on the effect it has on SARC cell proliferation." (PMID 39774004, 2024). "Top1ccs have been mapped at nucleotide levels at replication origin of Lamin B2 gene at late G1 and G1-S transition in human cancer cells." (PMID 38787953, 2024). "Among the 24 cancer types investigated, we found both B‐type lamins: lamin B1 and lamin B2 showed significant enrichment in tumor tissues (22/24 and 23/24 tumor types investigated, respectively), but LMNA was only enriched in 9/24 cancer types." (PMID 37218524, 2023). "Collectively TLM_CFM-F_OSM demonstrated a superior anti-cancer effect, thereby decreasing the protein expression of lamin B2, SOD, STAT3, and NFKB." (PMID 35745729, 2022). "It has been demonstrated that lamin B1 and lamin B2 are up- and down-regulated in several cancer cells and, accordingly, play different roles in cancer onset and development." (PMID 35132494, 2022). "Pairing the tumor tissue with the adjacent tissue and performing a paired Wilcoxon’s test revealed that the LMNB2 protein expression in the cancer tissue was significantly higher than that in the adjacent tissue (P < 0.001)." (PMID 33782407, 2021). "Western blot and qPCR analysis also showed high lamin B2 expression in 20 NSCLC cancer tissues than in adjacent normal lung tissues." (PMID 29285216, 2017). "In conclusion, LMNB2 may be a potential predictor of immunotherapy efficacy for these types of cancer." (PMID 39774004, 2024). "We showed that LMNB2 can play a crucial role in cancer immunity." (PMID 39774004, 2024). "First, we analyzed the expression of LMNB2 indifferent cancer types by mining the TCGA database." (PMID 39774004, 2024). "These functions and pathways are closely-associated cancer development, indicating that LMNB1 and LMNB2 could affect HCC progression through multiple cellular functions and signaling pathways." (PMID 36405011, 2022). "Moreover, it has been recently reported that also lamin B2 is involved in HCC cancer development promoting cell proliferation, migration, and invasion in HCC cell lines and in primary HCC cells." (PMID 35132494, 2022). "The results demonstrated that LMNB2 may modulate the immune response across cancers." (PMID 39774004, 2024). "However, the relation between LMNB2 expression and cancer progression is still poorly understood." (PMID 39774004, 2024). "However, the precise relationship found between Lamin B2 and AMPK is unknown in cancer studies, and only very few studies have been conducted to investigate the role of Lamin B2 in cancer progression." (PMID 35745729, 2022).
tumor (17 papers, 2017 to 2025). "The univariate cox analysis revealed that LMNB2 expression(P<0.001), tumor metastasis (P<0.001) and tumor multifocality (P<0.001) showed significant association with the OS rate in SARC." (PMID 39774004, 2024). "Additionally, key clinical characteristics, including pathological and histological grade, AFP levels, and tumor size, showed a close association with LMNB2 expression." (PMID 40483310, 2025). "The relation between LMNB2 expression and tumor mutational burden (TMB) was analyzed." (PMID 39774004, 2024). "Elevated expression of LMNB2 was associated with tumor immune cell infiltrates and poor OS in HCC." (PMID 36405011, 2022). "In vivo experiments also confirmed that silencing of NOP2 inhibited tumor growth, metastasis, as well as LMNB2 expression." (PMID 40366008, 2025). "In the 26 pairs of clinical CRC samples, we measured the expression of LMNB2 and confirmed the higher LMNB2 level in tumor samples than in normal samples." (PMID 40366008, 2025). "The transcriptome analysis showed that the COAD tumors had more lamin transcripts than normal tissue, supporting the upregulation of LMNA, LMNB1, and LMNB2 expressions in tumor tissues." (PMID 40708945, 2025). "Precise targeting of its key nodes, for instance, the SGK1-RIPK1-necroptosis axis, the LMNB2-PD-L1 axis, or specific immune cell subsets, is a new direction for overcoming immunotherapy resistance and inhibiting tumor metastasis in the future." (PMID 41375072, 2025). "LMNB2 overexpression attenuated the YY2 tumor suppressive effect, while blocking caspase‐1/GSDMD activation, IL‐1β levels, and cell death rate." (PMID 39903759, 2025). "Collectively, these data indicate that elevated LMNB2 levels promote tumor growth both in vitro and in vivo." (PMID 40483310, 2025). "Subsequently, we examined the effect of LMNB2 overexpression on the YY2 tumor suppressive potential in vivo." (PMID 39903759, 2025). "The association among LMNB2 expression level and immune cell infiltration, microsatellite instability (MSI) and tumor mutational burden (TMB) were analyzed." (PMID 39774004, 2024). "The correlation between the LMNB2 gene and tumor stem cells was measured by the DNA stem cell score (DNAss) and RNA stem cell score (RNAss) based on the DNA methylation pattern and mRNA expression respectively." (PMID 39774004, 2024). "In the multivariate cox regression analysis, LMNB2 expression(P=0.001), tumor metastasis (P<0.001) and tumor multifocality (P=0.014) showed significant correlation with the OS rate." (PMID 39774004, 2024). "These previous findings were consistent with our study, emphasizing that LMNB1 and LMNB2 play important roles in tumor progression." (PMID 36405011, 2022). "Representative images showed that knockout of LMNB2 resulted in a decreased staining intensity of LMNB2 and Ki67 in the resected tumor and an increased staining intensity of p21 compared with those of the control group." (PMID 33782407, 2021). "In this study, the expression of LMNB2 protein in CRC tissues was higher than that in adjacent tissues and the high expression of LMNB2 was related to tumor size, TNM stage, and lymph node metastasis." (PMID 33782407, 2021). "The miR-326 level of tumor increased markedly in the shSNHG1 group compared with control, whereas the expression of LMNB2 decreased." (PMID 34917510, 2021). "We analyzed 226 tumor and adjacent tissues, and immunohistochemical staining showed that LMNB2 was mainly located in the nuclear membrane of the nucleus." (PMID 33782407, 2021). "We tested the expression of LMNB2 in 12 pairs of tumor tissues and adjacent tissues, and found that LMNB2 expression was significantly increased in the CRC tissues." (PMID 33782407, 2021). "Tumor xenograft experiments showed diminished tumor growth with LMNB2 knockdown H1299 cells than with controls." (PMID 29285216, 2017).